FTO (FTO alpha-ketoglutarate dependent dioxygenase)
Diseases named in the same sentence as FTO in open-access papers (continued):
Sharing a sentence is not in itself a finding about the gene and the disease.
Obesity (continued). "Taken together, these studies suggest that the influence of FTO on obesity status may be operating in a neuropsychiatric fashion through the hypothalamus leading to loss of appetite control." (PMID 24719615, 2014). "Interestingly, a GWAS which included East Asians (Chinese, Korean, and Indonesian) including 27,715 obesity patient samples was able to replicate the previously identified FTO locus in European population in East Asian populations." (PMID 24719615, 2014). "Our data confirmed the role of FTO, CTNNBL1, LEPR and PPARG in obesity predisposition." (PMID 24879436, 2014). "In our study, the association between FTO and T2D did not decrease after adjustment for BMI as markedly as phenotypes such as obesity or sleep apnea." (PMID 25177340, 2014). "The associations of FTO rs9939609 with BMI and obesity did not appear until children reached 12–14 years." (PMID 24827155, 2014). "The FTO gene is a new candidate gene related to the development of fat tissue and obesity." (PMID 26290716, 2014). "Other studies also found that the FTO gene is associated with obesity or obesity-related diseases in non-schizophrenia populations." (PMID 25278160, 2014). "Recent studies have shown that the obesity‐associated SNPs embedded in the first intron of FTO are influencing expression of different, distant genes, called RPGRIP1L and IRX3, instead of affecting FTO itself." (PMID 25501432, 2014). "Moreover, genetic modulations of FTO in mice showed that overexpression results in obesity, while inactivation of the gene is protective." (PMID 24410832, 2014). "Mouse models lacking FTO gene function or expression exhibit increased energy expenditure and lean phenotype suggesting that loss of function protects against obesity in mice." (PMID 24719615, 2014). "Previous studies have observed similar results, but the mechanisms by which FTO SNPs influence obesity and obesity-related metabolic traits remains unclear." (PMID 25251416, 2014). "Strikingly, the GWAS variants associated with obesity showed association with levels of expression of IRX3 but not of FTO in human brain samples." (PMID 25473428, 2014). "Since obesity is known to be a predisposing factor for the development of T2D, it is not surprising that variants in FTO have also been found in T2D GWAS." (PMID 24719615, 2014). "Homozygotes for the risk allele of the most common SNP in FTO are 3–4 kg heavier than those without the risk allele and have a 1.67-fold increased risk of obesity." (PMID 25154910, 2014). "This means that the FTO risk allele has a dominant effect on individuals with higher BMI; hence the association was detected in severe obesity rather than in overweight population." (PMID 24911064, 2014). "Our findings are further supported by a recent study in children which found that the FTO variant rs9939609 showed association with obesity and BMI among girls but not among boys." (PMID 24879436, 2014). "We chose to experimentally validate the physical and functional interaction between miR-33 and FTO because the latter was recently discovered to be associated with obesity, and because this interaction has not been characterized in any species." (PMID 24626192, 2014). "Although the mechanism of most genetic loci predispose individuals to obesity is not clear so far, evidence indicated that they were involved in energy uptake (FTO, MC4R, PCSK1, and BDNF) and adipocyte differentiation (FTO, TMEM18, BDNF, MTCH2 and NEGR1)." (PMID 24626232, 2014). "Though results of our present study do not directly support the role of FTO in obesity risk, it is plausible that its effect on tuberculosis occurs through obesity-related immunocompetence." (PMID 25377722, 2014). "Knocking down expression of the obesity‐associated gene FTO in rat ventromedial hypothalamus did not affect energy balance." (PMID 25501432, 2014). "Joint effects between the FTO rs9939609 genotypes, obesity, and dietary preferences." (PMID 25110886, 2014).
Obesity (continued). "Our study of the group of individuals without severe obesity indicates an effect of FTO gene polymorphism on BMI in children with T1DM." (PMID 25214838, 2014). "Whether FTO is a good drug target for obesity is still an open question despite there being some undesirable effects of knocking it out." (PMID 23300482, 2013). "In this study, we recruited a large number of samples and identified that FTO is the susceptibility gene for PCOS regardless of the presence of obesity." (PMID 23840863, 2013). "Besides using a genetic risk score, we separately analyzed effects of two well-established obesity loci, FTO and MC4R, on BMI." (PMID 24040077, 2013). "Interestingly, although FTO showed an overall association with obesity, the strongest and most significant association was observed for class III obesity (Padd = 4×10−6)." (PMID 23950976, 2013). "However, it has turned out that newer BMI/obesity-associated loci have substantially smaller effects than does FTO, even though they provide further insight into the biology of the BMI/obesity phenotype." (PMID 23360386, 2013). "The fact that the majority of studies has failed to associate the FTO variants with obesity related trait, indicates that this gene is in a very close relationship with obesity and fat mass." (PMID 24289790, 2013). "It will be interesting to verify the effect of the obesity gene locus on milk energy content in humans, which might impact infant nutrition during breast feeding, and to test if the FTO region affects not only body fat but also lean mass." (PMID 23691044, 2013). "Our findings indicate that rs9939609 in the FTO gene is associated with pancreatic cancer risk in Japanese subjects, possibly through a mechanism that is independent of obesity." (PMID 23835106, 2013). "Overexpression of FTO in mice leads to obesity and the accompanying increase in adiposity." (PMID 24019958, 2013). "Interestingly, we confirmed the effect of the FTO locus on obesity in adult indigenous Mexican populations, despite of lower frequency of risk allele as compared to Europeans." (PMID 23950976, 2013). "In addition, 7 of the 17 (41.2%) GWAs-selected genes (FTO, TMEM18, INSIG2, FAIM2/BCDIN3, BDNF, SH2B1 and MC4R) were associated with obesity in this population." (PMID 23950976, 2013). "Among them, FTO, MC4R, MTCH2 and HTR2C are the main associated loci with BMI and obesity." (PMID 24267414, 2013). "The role of FTO in obesity has been further confirmed by transgenic manipulation in mice." (PMID 24345215, 2013). "The functional mechanism of FTO in obesity remains far from clear." (PMID 23360386, 2013). "Obesity is associated with hyperandrogenism and menstrual disturbance of PCOS and worsens PCOS complications such as T2DM, we hypothesize that FTO should be one of the molecular determinants linking obesity to PCOS." (PMID 23840863, 2013). "Variants in the FTO gene have been associated with obesity in children, but this association has not been shown with other biomarkers." (PMID 24289790, 2013). "The results indicate that regular meal frequency attenuates genetic predisposition to increased BMI in terms of both single gene variants (FTO rs1421085 and MC4R rs17782313) and a multiple-locus indicator (a genetic risk score based on eight obesity-susceptibility loci)." (PMID 24040077, 2013). "The FTO gene, located on chromosome 16q12.2, and the MAF gene, located on chromosome 16q22-23, were identified as genes harboring common variants with an impact on obesity predisposition." (PMID 23840443, 2013). "A recent meta-analysis including both adults and children concluded that physical activity attenuated the effect of FTO variants on obesity risk in adults but not in children." (PMID 24040077, 2013). "We confirmed the previously reported association of genetic variability in intron 1 of the FTO gene with the risk of obesity and without association with other related traits of inflammation and CVD risk biomarkers." (PMID 24289790, 2013).
Obesity (continued). "A recent meta-analysis reported that physical activity attenuated the influence of FTO variants on obesity risk in adults, but not in adolescents and children." (PMID 23094032, 2012). "The current study focused on variants located within and around FTO, MC4R and TMEM18 that are amongst the genes most strongly associated with obesity traits and also identified in earlier meta-analyses, despite the fact that the variance explained by these loci is small (1–2%)." (PMID 22723994, 2012). "Although multiple association studies as well as functional experiments have revealed that FTO is critical for obesity and 2DM, only one study with really small sample size has reported that FTO is assocaited with increased rifk for acute coronary syndrome, a severe form of CAD." (PMID 22697793, 2012). "In the genetic determinism situation, if a subject is a carrier of the risk alleles of the FTO and the MC4R polymorphisms, such genetic susceptibility would irreversibly determine the obesity phenotype, and that genetic influence would be totally independent of lifestyle factors." (PMID 23284998, 2012). "It is also conceivable that the nucleic acid demethylation activity of FTO on DNA might regulate the expression of genes involved in metabolism and that dysregulation of this process might lead to obesity at an epigenetic level." (PMID 22454631, 2012). "The precise mechanism by which the FTO gene leads to obesity development is unclear." (PMID 23134754, 2012). "Of particular interest is the fact that the FTO variants do not seem to affect BMI or the risk of obesity in African American, Chinese Hans or Oceanic populations." (PMID 23134754, 2012). "Amongst the adiposity-related genetic variants, we chose single nucleotide polymorphisms (SNPs) within the most common major adiposity genes FTO, MC4R and TMEM18, all of which have been recognized to be associated with obesity and explaining a variance of about 1–2%." (PMID 22723994, 2012). "Among the recent publications examining GEIs of GWAS loci, the majority of observational studies evaluated whether dietary components and physical activity interact with variation in the FTO gene for their effect on obesity." (PMID 24392269, 2012). "While these results are preliminary we suggest that our observations may provide the foundation for a mechanism that links FTO expression and the development of human obesity." (PMID 22675562, 2012). "However, on considering the aggregate score of the MC4R rs17782313 and FTO rs9939609, we did observe a statistically significant interaction both for BMI and for obesity." (PMID 23284998, 2012). "In a previous study of elderly men, the FTO rs9939609 minor allele was neither associated with obesity or BMI." (PMID 21637715, 2011). "Here, we examine the genetic effects of FTO and MC4R variants on obesity-related phenotypes." (PMID 19822564, 2011). "It is unclear whether the association effect acts through FTO or the adjacent FTM gene and the precise role of the FTO locus in obesity needs further investigation." (PMID 21466928, 2011). "Functional studies have demonstrated the direct effect of FTO on obesity." (PMID 22125610, 2011). "The FTO gene has recently attracted much attention in obesity research." (PMID 21651756, 2011). "We expected that the effects of FTO and MC4R on body fat mass would be more apparent if the population were stratified by SCM type, as a previous report has demonstrated distinct susceptibilities to obesity among subjects with different SCM types." (PMID 19822564, 2011). "Carrying a change in the FTO gene is common (found in three-quarters of Europeans and North Americans) and is associated with a 20%–30% increased risk of obesity." (PMID 22069379, 2011).
Obesity (continued). "Nine loci have been associated with extreme obesity at the genome-wide level, five of them influencing BMI / waist circumference as well as risk for extreme obesity (FTO, MC4R, TMEM18, MSRA, NPC1), four loci being more specific of genetic risk for extreme obesity (MAF, PTER, PRL, SDCCAG8)." (PMID 22043164, 2011). "This study reminded us that FTO might be a common genetic factor influencing not only obesity phenotypes, but also osteoporosis phenotypes, like BMD." (PMID 22125610, 2011). "On the contrary, a significant gene x education interaction has been found for the intron 1 variant in FTO, the significant effect of the SNP on BMI and obesity risk being restricted to subjects with no university education." (PMID 22043165, 2011). "Specifically, when certain ethnic populations have fewer members with TE type and more members with SY and SE types, the relationship between the FTO gene and obesity may become weak." (PMID 19822564, 2011). "The results therefore strongly suggest that FTO and MC4R might be the only two major-effect genes for obesity with common variants in populations of European ancestry." (PMID 21552555, 2011). "Aside from FTO, GWA studies associated with obesity yet another gene, named TMEM18." (PMID 20380707, 2010). "The limited expression studies in humans found no clear association between obesity-related SNPs and the FTO mRNA expression levels in adipose tissue and skeletal muscle." (PMID 21103374, 2010). "The remaining 3 FTO polymorphisms were significantly associated with obesity in whites but not in African-Americans." (PMID 20502638, 2010). "It is conceivable, therefore, that the nucleic acid demethylation activity of FTO might regulate the expression of genes involved in metabolism and that dysregulation of this process might lead to obesity." (PMID 20381893, 2010). "Among those genes, FTO explained the largest variation of BMI and obesity." (PMID 20858286, 2010). "The phenotypic characterization of both the Fto−/− and FtoI367F mice support the idea that association of FTO SNPs with human obesity arises via regulatory or functional effects on FTO rather than other genes in the region." (PMID 20381893, 2010). "In addition, we assessed the effect of the markers in 31,182 obese, lean, normal weight, and unselected individuals from population-based samples and showed that the variants near FTO, MC4R, TMEM18, and SDCCAG8 were consistently associated with obesity." (PMID 20421936, 2010). "The TCF7L2 obesity association was stochastically independent of the FTO association if assessed in a multiple regression analysis." (PMID 20092643, 2010). "As reduced FTO function decreases body weight in mice, it is worth exploring if pharmaceutical agents that inhibit FTO activity might help reduce human obesity." (PMID 19680540, 2009). "Common variants in the FTO gene and near the MC4R gene are associated with modest, yet consistent effects on BMI (0.2-0.4 kg/m2 per allele) that translate into odds ratio of 1.1-1.3 for obesity." (PMID 20017980, 2009). "There is an interaction between physical activity and the effect of the FTO genotype on BMI levels suggesting that lack of physical activity is a requirement for an association of FTO gene variants to obesity." (PMID 20003232, 2009). "The functional relevance of FTO to obesity is currently under investigation." (PMID 19259258, 2009). "Data from studies in Asians did not initially seem to support a role of FTO variants in obesity in such populations." (PMID 19265514, 2009). "Four studies have so far analyzed if the effect of FTO on obesity in adults may be changed upon physical activity with somewhat contrasting results." (PMID 20003232, 2009). "As the mice maintained on sucrose for 3 weeks gained more weight than chow-fed controls, it also indicates that the development of overeating-driven obesity is not a causative factor in changes in FTO expression." (PMID 19860904, 2009).
Obesity (continued). "For example, a gene variant in the non-coding region of FTO enhances obesity risk, but it is not clear if this is an effect of the FTO gene itself or another gene located nearby." (PMID 19680540, 2009). "Here we found that the well established obesity risk allele for a common variant in FTO does not associate with increased BMI levels in a Swedish population of adult men which reached adulthood before the appearance of today's obesogenic enviroment." (PMID 20003232, 2009). "Our results lend further support for the role of the FTO gene in obesity, suggesting that interventions at the FTO pathway level may be of value in patients who suffer from this disease." (PMID 18335027, 2008). "Additionally, several other SNPs in the intronic region of FTO, that are in strong linkage disequilibrium (LD) with rs9939609, showed similar effects on both childhood and adult obesity." (PMID 18799002, 2008). "This FTO gene is responsible for 1% of the total heritability of obesity." (PMID 19112512, 2008). "An intriguing observation is that it catalyzes Fe(II)- and 2OG- dependent DNA demethylation, although the role of FTO related DNA methylation in obesity is unknown." (PMID 18218107, 2008). "The FTO SNPs have previously been shown to be relevant for obesity in both children and adults." (PMID 18159244, 2007). "This computational prediction of the function of FTO should suggest further steps for its experimental characterization and help to formulate hypothesis about the mechanisms by which it relates to obesity in humans." (PMID 17996046, 2007). "A lower expression of FTO in TT genotype carriers has been reported, which could contribute to decreased adipogenesis and limited energy storage by adipocytes, compared to AA genotype carriers, in which elevated adipose storage or obesity is observed." (PMID 41141248, 2025). "Epidemiological observations linking maternal overweight/obesity to altered milk miRNA profiles and to early infant adiposity are, therefore, compatible with a model in which milk miRNA abundance, Wnt pathway methylation status, and FTO-mediated m6A dynamics lead to adipocyte lineage outcomes." (PMID 41300824, 2025). "FTO is the first identified m6A demethylase and primarily functions to remove m6A methylation through its oxidative demethylase activity, playing critical roles in a variety of pathological conditions, including obesity, diabetes, heart failure, neurological disorders, and tumorigenesis." (PMID 40234389, 2025). "9939609T allele of the FTO gene could be a protecting factor against obesity as a negative association was found between this allele and overweight in ALL survivors who received CRT." (PMID 41228239, 2025). "Associations between variants in the FTO locus and plasma concentrations of appetite related hormones are inconsistent, and might not work in a dose dependent fashion in people with obesity." (PMID 39792913, 2025). "Therefore, the FTO gene ought not to be grouped with genes that have a direct and thoroughly defined mechanistic association with monogenic obesity." (PMID 40428329, 2025). "Interestingly, the FTO gene, a genetic key player in obesity, may provide a genetic link between these obesity-related metabolic disturbances and cancer, thereby offering a potential explanation for the observed association between obesity and tumorigenesis." (PMID 40040878, 2025). "Despite differences in study methods, these findings suggest that FTO gene polymorphisms may influence the development of cataracts through mechanisms independent of obesity." (PMID 41315216, 2025). "Although there are hundreds of studies validating this association signal with obesity risk, it is becoming clear that the FTO gene itself may not be the causal effector gene at this key associated signal." (PMID 39421299, 2024).